CDKL4 (cyclin dependent kinase like 4)
Tractability: Small molecule: it belongs to a druggable protein family.
Target class: Enzyme; Transferase
Gene: Protein-coding gene on chromosome 2 (39,168,045 to 39,243,983, reverse strand). Ensembl gene ENSG00000205111.
Subcellular location: Cytoplasm
Gene Ontology:
Molecular function: ATP binding; cyclin-dependent protein serine/threonine kinase activity; protein kinase activity; protein serine kinase activity
Biological process: regulation of cell cycle
Cellular component: cytoplasm
Genetic constraint (gnomAD): Loss-of-function variants: 22 observed, 23.59 expected, observed/expected ratio (o/e) 0.93, 90% interval 0.67 to 1.33. The upper end of that interval is the gene's LOEUF score, 1.33, which puts it in group 5 of 6, group 1 being the genes least tolerant of losing a copy. Missense variants: 230 observed, 224.06 expected, observed/expected ratio (o/e) 1.03, 90% interval 0.92 to 1.14. Synonymous variants: 79 observed, 79.57 expected, observed/expected ratio (o/e) 0.99, 90% interval 0.83 to 1.2.
Homologues: Orthologues: pig CDKL4 (95% identical), dog CDKL4 (94% identical), guinea pig CDKL4 (92% identical), mouse Cdkl4 (92% identical), rat Cdkl4 (91% identical), chimpanzee CDKL4 (89% identical), rabbit CDKL4 (81% identical). Paralogues in human: CDKL1 (66% identical), CDKL2 (51% identical), CDKL3 (45% identical), CDKL5 (44% identical), CDK1 (34% identical), CDK3 (34% identical), CDK2 (34% identical), CDK5 (33% identical), CDK12 (33% identical), CDK13 (33% identical), CDK10 (32% identical), CDK7 (32% identical), and 14 more.
Diseases named in the same sentence as CDKL4 in open-access papers:
CDKL4 is named in the same sentence as 6 diseases in open-access papers, as found by Europe PMC text mining. Sharing a sentence is not in itself a finding about the gene and the disease. The quoted sentences say what the papers report.
chordoma (1 paper, 2017). Chordomas are rare malignant tumors arising from embryonic remnants of the notochord in axial skeleton. "ULK4, NPR1 and CDKL4 were the top most expressed kinases in the Chor-IN-1 cell line, while FGFR3, KDR and WNK2 were less expressed or absent in Chor-IN-1 cells as compared to the other chordoma lines." (PMID 28835717, 2017).
colon cancer (1 paper, 2015). "Consistent with this, our HT-RNAi screen results showed increased colon cancer cell death after targeting CDKL4 in the presence of oxaliplatin." (PMID 25904054, 2015).
tumor (1 paper, 2020). "Among all CDKLs, CDKL3 and CDKL4 showed significantly enhanced expression in tumor samples compared with adjacent non-tumor tissues." (PMID 32234750, 2020).
CDKL4 also shares sentences with these, for which no sentence is quoted: breast carcinoma (1 paper); colorectal cancer (1); glioblastoma (1).